MYC (MYC proto-oncogene, bHLH transcription factor)
Diseases named in the same sentence as MYC in open-access papers (continued):
Sharing a sentence is not in itself a finding about the gene and the disease.
tumor (continued). "We further confirmed the MYC(N) dependency in a panel of tumor cell lines and primary tumor cells manifesting differential MYC(N) levels." (PMID 38493213, 2024). "Here, we demonstrate that liver tumors initiated by the transgenic expression of MYC take up larger amounts of Trp than normal liver tissue and generate I3P, which functions as an oncometabolite that drives tumor growth." (PMID 38769298, 2024). "Further analysis into the “WT” group revealed a subset of 21 tumours which had 42 genes with their expression inversely correlated with MYC expression." (PMID 38877600, 2024). "USP9X antagonizes the ubiquitination of FBW7, and its deletion leads to the destabilization of FBW7, resulting in increased levels of c‐MYC and enhanced tumor proliferation." (PMID 39678489, 2024). "To test this, we analyzed the effect of SNX631-6 on MYC-CaP-CR tumor growth in immunodeficient NSG mice." (PMID 38546787, 2024). "Instead, we found that MYC(N)-high tumor cells and tumor models in vivo were addicted to NUDT1 function." (PMID 38493213, 2024). "In regard to MYC signature shutdown, immune-activating and tumor-suppressive phenotypes were more profound in patients from DL5 than from DL3." (PMID 38321218, 2024). "Nevertheless, when MYC was suppressed in the host with a compromised immune system, there was a reduced rate of elimination of tumor cells, the partial shrinkage of tumors, and the eventual recurrence of tumors." (PMID 38473324, 2024). "MYC-driven cancer cells, in which RS is limited and tumor growth is supported by ATR/Chk1 activation, exhibit higher sensitivity to ATR and Chk1 inhibitors." (PMID 39456601, 2024). "MYC depends on its binding partners for function, but it was unclear which of these are most relevant for oncogenic growth and tumour maintenance." (PMID 38821858, 2024). "Amongst them, two genes connected to lactate, namely secreted phosphoprotein 1 (SPP1) and MYC proto-oncogene (MYC), are significantly increased by more than four times in the tumor samples." (PMID 38397058, 2024). "MYC inactivation causes HCC stem cells to differentiate, which leads to a decrease in tumor markers and an increase in hepatocytes, cytokeratin 8, and liver stem cell cytokeratin indicators." (PMID 39547513, 2024). "The network of the most promising miRNA-target interactions showed that several tumor suppressor and oncogenic miRNAs target and regulate critical genes, including MYC, CREB1, TIMP3, CCNE1, and TGFB1, which were shown to be involved in WT pathogenesis." (PMID 39473825, 2024). "A high prevalence of group 3 tumours shows overexpression of the MYC oncogene, making it a potential therapeutic target." (PMID 39766063, 2024). "USP29 stabilizes MYC and hypoxia-inducible factor 1-alpha (HIF1α); therefore, it enables tumor cells to respond to both normoxia and hypoxia." (PMID 39664521, 2024). "Numerous BET inhibitors, particularly the BRD4 inhibitor JQ1, have demonstrated the ability to downregulate MYC and impede tumor growth in various animal models with MYC activation." (PMID 38383388, 2024). "Altogether, this creates a strong dependency of cancer cells on MYC and it has been demonstrated that indeed MYC withdrawal leads to tumor regression." (PMID 37519063, 2023). "Tumors in the various groups were histologically indistinguishable and consisted of densely packed, small basophilic-staining tumor cells, as previously reported for c-MYC/Mcl1 mice." (PMID 37040183, 2023).
tumor (continued). "E2F_targets and MYC_targets_V1 also involve tumor therapy, drug resistance, immune evasion, and progression." (PMID 37745301, 2023). "Results showed that the growth rate and weight of tumors induced by c-MYC S405A cells were significantly lower than tumors induced by c-MYC WT cells, and the c-MYC S405A mutant abrogated the NEK8-mediated increase in tumor proliferation ability." (PMID 37596667, 2023). "Our findings reveal glycosylation as a new medium through which MYC manipulates the tumor microenvironment." (PMID 36897988, 2023). "Subsequently, the NICDs activate the transcription of target genes, including the HES family and MYC, which has been known to contribute to tumor stemness and metastasis." (PMID 37853162, 2023). "Combined high expression of MYC and ST6GALNAC4 identifies patients with high-risk cancers and reduced tumor myeloid infiltration." (PMID 36897988, 2023). "Our data indicate that the growth of Ctdnep1-deficient tumor cells depends on MYC levels, which is in keeping with a critical role of MYC in tumor cell proliferation and chromosome instability." (PMID 36765089, 2023). "Comparable observations were made between the TAL and RMC populations of the naive tumour with loss of TFCP2L1 activity and gain of MYC and NFE2L2/3 activity." (PMID 37236926, 2023). "The PP2A serine/threonine phosphatase is frequently inhibited in most human cancers, and it primarily functions as a tumor suppressor by diminishing the activation of key oncogenic regulators, including MYC, ERK and AKT." (PMID 37755397, 2023). "Treatment of NB tumors with SF1126 also reduced MYC expression and inhibited growth in vivo, leading to tumor shrinkage and reduced neovascularization." (PMID 36839989, 2023). "In BCa, IGF2BP1 promotes tumour proliferation, migration and invasion by regulating the expression of MYC and FSCN1." (PMID 36747239, 2023). "The combination treatment reduced p-AKT and MYC expression, decreased FS and OS tumor volumes, and suppressed lung metastases of OS." (PMID 37173935, 2023). "Apart from its cell-intrinsic role in tumorigenesis, MYC plays a crucial role in shaping the tumor microenvironment and establishing a nurturing niche for cancer cells." (PMID 37755397, 2023). "Mechanically, LC-MS, CoIP, and rescue experiments revealed that GINS2 promoted tumor progression through the STAT3/MYC axis in the OS." (PMID 36873736, 2023). "In line with MYC is a well-known oncogenic factor in cancer, our findings provide a new target particularly in MYC-related tumor." (PMID 37041291, 2023). "This demonstrated our Myc-knockin GEMM closely resembled the high-MYC-expressing human OS tumor subtype with 3,147 positively and negatively enriched overlapping gene sets between mouse and human samples." (PMID 37279073, 2023). "It is able to directly and selectively deubiquitinate and stabilize MYC and HIF1α, and consequently induce an adaptive response of tumor cells in both normoxia and hypoxia." (PMID 37443779, 2023). "Our results support previous studies which reported lower expression of MYC in normal vs. tumour tissue." (PMID 37400829, 2023). "Its activation is also generally essential for tumorigenesis as shown in several animal models of cancer in which MYC alteration is required for tumor initiation, progression or maintenance." (PMID 37755397, 2023).
tumor (continued). "Histological examination confirmed emerging tumors to express MYC and to be solid ILCs, consistent with the predominant tumor type emerging from mammary glands of K14-Cre;Cdh1F/F;Trp53F/F female mice." (PMID 37642941, 2023). "In this review, we summarize the essential role of the MYC signaling pathway in tumor immunity and the development status of MYC-related therapies, including therapeutic strategies targeting MYC and combined MYC-based immunotherapy." (PMID 36966168, 2023). "First, ssCHK1 and ssBRD4 hindered G1/S transition cell cycle progression by depleting MYC and cyclin D1 levels, while simultaneously upregulating tumor suppressor genes in HCC, preventing cell growth in target cells." (PMID 36684069, 2023). "In another example, COSMIC fusion PVT1:MYC was originally identified by STAR-Fusion in 20 samples (14 TCGA tumor, 1 TCGA normal, and 5 GTEx samples)." (PMID 37323575, 2023). "Using the GSEA method, the high-risk group was mainly distributed into the E2F, G2M checkpoint, and MYC targets, which were closely related to interactions on angiogenesis, extracellular matrix remodeling, and tumor cell-endothelial cell interactions." (PMID 37063853, 2023). "MYC expression varied from case to case, detected in 20 to 60% of tumor cells but always displaying weak staining." (PMID 37555980, 2023). "MYC is a ‘master regulator’ of glycolysis and tumour proliferation, which can transcriptionally upregulate several key genes involved in aerobic glycolysis like HK2 and PKM2." (PMID 36752127, 2023). "Since the expression of MYC targets V1 geneset was increased in the hybrid tumor, we aimed to determine if this upregulation is attributed to the enhanced activity of the c-Myc transcription factor." (PMID 37848444, 2023). "While different RhOMEs loop to the MYC promoter in different tumors (intertumoral heterogeneity), we find preferential use of one or a combination of RhOMEs within the same tumor." (PMID 38040699, 2023). "(v) is it possible to define a unique MYC transcriptional signature shared across various tumor types?" (PMID 37457123, 2023). "It remains therefore necessary to find other ways to broaden the repertoire of molecules to target the functions of c-MYC in tumor cells." (PMID 37035206, 2023). "Several tumor-promoting genes, including MYC and MDM2, are thought to be involved in the disease progression." (PMID 37511127, 2023). "Among multiple crucial functions, MYC is involved in RNA metabolism (mRNA splicing, stability and translation efficiency), which is necessary for tumor cells growth." (PMID 36597789, 2023). "Two independent studies revealed positive correlations between the c-MYC protein levels and sub-cellular localization with tumor size and tumor classification, respectively." (PMID 36765581, 2023). "Various ligands targeting G4 have been tested to regulate MYC expression, some of which led to a decrease in tumor growth, which correlated with a decrease in MYC and other oncogenes expression." (PMID 37111301, 2023). "MYC proto-oncogene (MYC) is a transcription factor among the most commonly activated oncoproteins, playing vital roles in lipid metabolism and tumor aggressiveness with broad effects." (PMID 37151387, 2023). "A preclinical trial showed that arginine depletion with pegylated arginine deiminase (ADI-PEG 20) suppresses tumour growth in mice that had MYC-driven tumours." (PMID 37870696, 2023). "Transgenic overexpression of MYC in mice leads to increased proliferation and tumor development in multiple tissues." (PMID 37731815, 2023).
tumor (continued). "MYC can promote immune-suppression via inhibition of tumor cell-intrinsic STING-IFN-I signaling in breast cancer." (PMID 37898690, 2023). "BET inhibitor (BETi) proteins, including BRD2, BRD3, BRD4, and BRDT, have been shown to inhibit MYC proliferation in various tumor models." (PMID 36966168, 2023). "Building on these promising results in tumor tissue samples, DNA was isolated from CSF samples of five MB patients with MYC amplification (n = 49)." (PMID 37173990, 2023). "After receiving vesicles, c-MYC is upregulated in CAFs, inducing the reprogramming metabolism to promote tumor growth." (PMID 36721232, 2023). "The analysis of human tumor specimens for MSI2 correlated with MYC expression and MSI2 expression was elevated in late-stage HCC (stage III–IV)." (PMID 37117191, 2023). "Several mouse models have convincingly demonstrated a tumor-driving role of MYC in the development of Group 3 MB." (PMID 37919824, 2023). "The main transcription factor in glycolysis pathway is c-MYC, while lncRNA FILNC1 can down-regulate c-MYC expression and repress the glycolysis pathway and tumor progression through interaction with AUF1 under energy stress." (PMID 36969848, 2023). "Undoubtedly, an in-depth understanding of the mechanism of action of the MYC gene family in tumor immunity and its application in tumor immunotherapy will be crucial to the development of effective cancer therapies." (PMID 36966168, 2023). "This depends on the absence or presence of the transcriptional corepressor brain acid-soluble protein 1 (BASP1) that converts the WT1 oncoprotein into a tumor suppressor, thereby also blocking transcriptional MYC activation." (PMID 36969025, 2023). "Previous studies have also shown that PUS7 and DCK1 regulation of MYC expression promotes tumor malignancy." (PMID 37925171, 2023). "CDK4/6 inhibition was shown to downregulate homologous recombination, sensitising breast and ovarian cancer cell lines to PARP inhibition to inhibit cell growth, particularly in tumours with high levels of MYC expression." (PMID 37430137, 2023). "In mice bearing MV4-11 xenografts, compound 106 can reduce the expression of c-MYC even at free plasma concentrations lower than 0.2 μM and lead to an almost complete tumor regression at a dose of 10 mg/kg." (PMID 37142850, 2023). "Deregulation of the MYC family of transcription factors c-MYC (encoded by MYC), MYCN, and MYCL is prevalent in most human cancers, with an impact on tumor initiation and progression, as well as response to therapy." (PMID 37760568, 2023). "The leading compound is the HDAC6 inhibitor, which acts via the hyperacetylation of MYC (K148ac), strongly inducing its proteasomal degradation via the parallel sensitization of tumor cells to ionizing radiation." (PMID 37443779, 2023). "Through its transcriptional activity, MYC orchestrates a variety of molecular changes that contribute to the development of a tumor-permissive microenvironment and educating tumor-infiltrating cells." (PMID 37755397, 2023). "A novel tumor suppressing role for RUNX3 is shown where a direct interaction with MYC leads to disruption of MYC-MAX heterodimers and consequent degradation of the MYC oncoprotein." (PMID 37400551, 2023). "Targeting MYC is promising for restoring immune response, modulating the tumor microenvironment and improving cancer patient outcomes." (PMID 37755397, 2023).
tumor (continued). "The importance of MYC is also underscored by the fact that repression of MYC can result in fast regression of tumors in animal models, making it a promising target for tumor therapy." (PMID 37601651, 2023). "We also observed that c-MYC, a key CSC regulatory protein and transcriptional factor implicated in promoting tumor growth and cancer stemness, is markedly reduced in SUM159-shXIST but not SCR cells following DOX treatment." (PMID 36922677, 2023). "MYC inhibition reverses the immunosuppressive tumor microenvironment, restores immune cell activation and enhances the production of immune-stimulatory molecules." (PMID 37755397, 2023). "Second, our findings indicate a positive correlation between the lactate score and the MYC signaling pathway, which holds significant implications for tumor immune evasion and immune checkpoint regulation." (PMID 37790933, 2023). "By increasing the expression of miR-9, c-MYC caused the downregulation of E-cadherin and activation of β-catenin signaling, thus inducing the upregulation of VEGF and the tumor angiogenesis." (PMID 36721232, 2023). "RNA‐seq was performed on 73 cases of EBVaGC samples from the SYSUCC cohort, and a hallmark enriched pathway analysis prompted that FTO expression was positively correlated with MYC pathway in EBVaGC tumour tissues." (PMID 38082402, 2023). "As the activation of c-MYC contributes to the progression of multiple types of cancer, this study implies a general tumor-promoting role of OTUB1." (PMID 38264570, 2023). "Taken together, these data provide direct evidence that KDM4B epigenetically enhances MYC stability and shed new light on its oncogenic activity in tumor development." (PMID 38093312, 2023). "ERK phosphorylation can activate tumour-promoting transcription factors such as NF-κB, MYC, and β-catenin, leading to gene expression." (PMID 37324453, 2023). "We next analyzed cell death and proliferation during early B cell differentiation in pre-tumor stage λ-MYC mice." (PMID 37809061, 2023). "Arginine depletion with PEGylated arginine deiminase has been found to dramatically suppress the tumor growth of MYC-driven SCLCs in genetically engineered mouse models and a patient-derived xenograft from a relapsed SCLC patient." (PMID 37422534, 2023). "Based on studies of MYC transcriptional repressors, subsequent studies on a series of effects of MYC in tumor models and analyses of the transcriptional targets of MYC oncoproteins have been performed." (PMID 36966168, 2023). "Subsequent analysis of a lung metastasis revealed increased copy number on chromosome 8p including c-MYC compared to the primary tumor." (PMID 36719686, 2023). "An important role of altered SMARCA4 in MB development was suspected before since the overexpression of SMARCA4 wild-type represses tumor development in an OTX2/MYC Group 3 MB mouse model." (PMID 37919824, 2023). "More importantly, CD47 is a more important “mediator” of MYC-mediated crosstalk between tumor cells and dendritic cells." (PMID 36966168, 2023). "For example, the RAS and MYC oncogenes can contribute to tumor incidence and progression through the lncRNA Orilnc1 and DANCR, respectively." (PMID 37915049, 2023). "In such a context, MYC targeting therapies are of special interest, as MYC withdrawal is expected to result in tumor regression." (PMID 37457123, 2023). "Predesigned and wet-lab validated probes for ddPCR were used to establish the detection method and were validated in two MYC-amplified MB cell lines as well as tumor tissue of the MYC-amplified cohort." (PMID 37173990, 2023). "The splenic B cell population in pre-tumor stage λ-MYC mice was significantly reduced relative to controls, both as a proportion of the total splenocytes and in terms of absolute numbers." (PMID 37809061, 2023). "The regulatory roles of MYC, mTOR, and E2F in tumor initiation and progression processes are widely recognized." (PMID 37759234, 2023).